MET (MET proto-oncogene, receptor tyrosine kinase)
Diseases named in the same sentence as MET in open-access papers (continued):
Sharing a sentence is not in itself a finding about the gene and the disease.
cancer (continued). "Unlike T24, 786-0 cells express both HGF and c-MET, representing a cancer early progenitor cell marker." (PMID 24797571, 2014). "In addition to known cancer driver genes such as ERBB2 (6% of cases), NRAS (3%), MET (3%), PIK3CA (1%), AKT2 (1%), TSC1 (1%), and ERBB4 (1%), several putative cancer genes were identified, such as PTPRC, SYNE2, GRIN2A, and CDH10." (PMID 24576404, 2014). "Crizotinib, a c-MET/ALK inhibitor, has exhibited antitumor efficacy in different types of cancers." (PMID 25193856, 2014). "Several MET inhibitors are in various phases of cancer clinical trials; however no studies to date have been reported using a combination of MET and PI3K inhibitors, especially in MPM." (PMID 25221930, 2014). "In the responsive group, 9 mutations (26%) were found in genes concerning proliferation pathways: PIK3CA (2 ADC with exon 9 E545K, and a poorly differentiated carcinoma with H1047R), BRAF (V600E in 2 ADC), STK11 (V197fs 69 in one ADC and F354L in one SCC), NTRK2 (L755L in a SCC) and MET (N375S)." (PMID 25561229, 2014). "MET is a proto-oncogene with its copy number (CN) alterations been reported in some cancers, but not in primary intestinal diffuse large B-cell lymphoma (PI-DLBL) yet." (PMID 23379953, 2013). "In malignant tumors, HGF is produced by stromal cells, while MET is expressed by cancer cells, which suggested in the mid-1990s that this paracrine loop may determine malignant behaviors." (PMID 23296269, 2013). "In addition, other (cancer) ‘stemness’ genes (like LGR4, SOX9, KLF5 and MET) are also upregulated in the pSP." (PMID 24069258, 2013). "Thus, inhibition of aberrant MET activation holds promise for the eradication of CSC, a key determinant for cancer recurrence after chemotherapy." (PMID 23296269, 2013). "Although no gene showed a positive correlation with EGFR or MET expression, eight and nine such genes displayed a negative correlation with EGFR and MET expression, respectively, in cancer samples." (PMID 22211244, 2012). "For the c-MET low expressing cells, like MCF-7, it needs to be clarified whether another protective pathway exist to support cancer cells resisting the treatment of NaBu." (PMID 22253909, 2012). "Taken together, all these observations might suggest to further investigate the usefulness of VEGFA, MET and TFRC as common cancer biomarkers." (PMID 22761861, 2012). "Our data show that cancer cells with mutant MET (not the wild type) and MET pathway activation via exogenously added HGF have an increased proliferation, invasiveness and colony formation capacity." (PMID 21847116, 2011). "The mechanism whereby HGF activation of c-MET leads to increased motility, migration, and invasion in cancer cells has not been well-defined." (PMID 17667909, 2007). "Else, PRSS22 was found to be not expressed in cancer cells (EGFR/FGFR2/MET/VEGFR) of GC patients." (PMID 41497316, 2025). "We further integrated cancer patient-derived organoid (PDO) data on drug sensitivity into the QSP framework and explored the translational utility of this hybrid drug analysis paradigm towards the design of optimal personalized treatment regimens for 5 NSCLC patients harboring MET amplification." (PMID 41368576, 2025). "Sequencing results showed that MET, EGFR, KMT2B and RET gene were mutated in LGFM, and KMT2B gene had cancer promoting effect, but there was no literature report in LGFM, which may be of certain significance for the diagnosis and treatment of LGFM." (PMID 38347522, 2024). "In the TRK inhibition field, adding crizotinib (with activity against METy) to TRK inhibition with selitrectinib led to the control of cancer progression driven by emerging MET amplification after entrectinib use not controlled by monotherapy with selitrectinib." (PMID 39410015, 2024). "The HGF/c-MET signaling pathway may be involved in various cellular processes, including carcinogenesis, proliferation, survival, metastasis, epithelial-mesenchymal transition (EMT), and drug resistance in cancer cells." (PMID 38238761, 2024).
cancer (continued). "Therefore, an in-depth study of HGF/c-MET mechanisms in the TME will enhance our biological perspective on tumors and provide a critical theoretical basis and potential targets for developing novel anti-cancer therapies." (PMID 39201787, 2024). "Indeed, four proteins (P08581|MET, P21860|ERBB3, P04626|ERBB2, and P25445|TNR6) from HCT116-specific group and one protein (P46531|NOTC1) from DKO1-specific group are oncogene products (cancer driver score = 4)." (PMID 36639722, 2023). "Thus, the O‐glycosylation sites on EGFR and MET initiated by GALNT2 could vary in different cancer types, which leads to differential effects of GALNT2 on the activities of EGFR and MET." (PMID 36409270, 2023). "Overall, these results directly define the HGF/MET axis as a driving force of the cell-autonomous metastatic process and suggest that it enhances the malignant phenotype by boosting pro-invasive cues, even when it is not the driver of cancer growth." (PMID 37345079, 2023). "The activation of the HGF/c-MET axis has been reported in various malignant tumors, regardless of whether there is a change in the MET genome." (PMID 37919751, 2023). "In a similar study of NTRK fusions in cancer patients, those harboring fusions with any of the 3 most frequent partners ETV6, TPM3, and LMNA comprised 22.3% (198/889) of all NTRK‐positive cases, a percentage closer to our observation with MET (13/122 patients, 10.7%)." (PMID 37326363, 2023). "They activate cancer cell signaling pathways and transcription factors, including IGF1/α6β4 complex, FGFR2, TIMP, DNA replication and mTOR signaling, Smad7, KLF4, and TBX2, and downstream proto-oncogenes such as MYC, MET, and CDK1, which facilitate cancer progression." (PMID 37046676, 2023). "As MET dependency has considerably affected the success and failure of MET-targeted clinical trials, additional studies are required to understand the role of MET Ser1016 phosphorylation in HGF-dependent cancers or cancers with lower levels of MET amplification." (PMID 37188738, 2023). "While the combination of the analysis of 5′/3′-end RET expression imbalance and variant-specific PCR allowed identification of RET translocations in approximately 2% of consecutive NSCLCs, this estimate approached 120/2361 (5.1%) in EGFR/KRAS/ALK/ROS1/BRAF/MET-negative carcinomas." (PMID 37445709, 2023). "Various studies demonstrated that the impressive anti-cancer effects could be achieved by inhibition of RTKs such as human epidermal growth factor receptor 2 (HER2), mesenchymal epithelial transition factor (c-MET), insulin-like growth factor 1 receptor (IGF1R) and many others." (PMID 35372044, 2022). "Eight studies performed sequencing through different cancer‐related gene panels, and nine studies sequenced only predesignated genes including EGFR, KRAS proto‐oncogene (KRAS), B‐Raf proto‐oncogene (BRAF), erb‐b2 receptor tyrosine kinase 2 (ERBB2), and MET proto‐oncogene (MET)." (PMID 36000927, 2022). "Considering that CPT inhibited cancer stemness by suppressing THEMIS2 expression and MET phosphorylation activation, we investigated whether the inhibition of endogenous THEMIS2 expression could affect the chemosensitivity of TNBC cells with effects mimicking those of the CPT treatment." (PMID 34974522, 2022). "Moreover, while VEGF inhibition has been often connected to tumor VCO, VEGF is also known to downregulate cancer cell invasion via enhanced recruitment of the protein tyrosine phosphatase 1B (PTP1B, which can directly dephosphorylate MET and VEGFR2), thereby suppressing cancer cell migration." (PMID 36119528, 2022). "Hence, neither antagonistic monovalent nor bivalent anti-c-MET mAbs show clinical benefits against cancer." (PMID 36233320, 2022). "The MET signaling pathway can be activated by multiple molecules, plexins, integrins, EGFR, and ERBB2, and the crosstalk between those pathways may contribute to cancer progression and drug resistance." (PMID 34761497, 2021).
cancer (continued). "Additional studies are needed to develop approaches for optimal identification of patients who would benefit from single-agent MET TKI treatment and to determine whether our observations extend to other cancers where MET amplification has been described as a drug resistance mechanism." (PMID 34516823, 2021). "Tivantinib could inhibit cell viability regardless of MET activation in cancer cells, thus microtubule inhibition might be the key mechanism of tivantinib-associated HCC growth inhibition." (PMID 34804015, 2021). "Therefore, targeting c-MET in cancer is hampered by a lack of diagnostics that accurately reflect high c-MET signaling and dependence." (PMID 34490234, 2021). "However, alternative receptor tyrosine kinases (EGFR, MET, HER2), post-translational processes (such as SUMOylation), IGF1R-EMT-independent pathways, and cancer–cell microenvironment interactions suggest that current preclinical models do not fully recapitulate the complex clinical scenario." (PMID 34065119, 2021). "The HGF/MET axis, along with interaction with other tyrosine kinases, can activate multiple signaling cascades in the cells, including Wnt/ß-catenin, Janus kinase/STAT, RAS/MAPK, PI3K/AKT, and Src, which among others can take a highly important role in cancer development." (PMID 34217156, 2021). "Moreover, GC-MSC could robustly express hepatocyte growth factor (HGF) as ligand of c‐MET to trigger phosphorylation of its downstream signaling cascade in cancer cells, and aberrant HGF/c-MET axis has been well-established to be critical for GC progression." (PMID 34046337, 2021). "On the other hand, monotherapy of targeting c-MET may be of no clinical importance, but the combinations of c-MET-targeted treatment have tremendous therapeutic potential for cancers." (PMID 34804015, 2021). "Combining MET and PARP inhibitors did not increase cancer cell death in vitro in this study; nevertheless, MET inhibition could still be a viable treatment option." (PMID 34069138, 2021). "The DEGs were significant enriched in cancer associated pathways including surfactant metabolism, signaling by receptor tyrosine kinases, signaling by PDGF, non-integrin membrane-ECM interactions, MET activates PTK2 signaling, and so on." (PMID 33542901, 2020). "However, the MET pathway is typically activated through paracrine cancer–stroma signaling, yet this interaction has not been investigated further to date." (PMID 32485915, 2020). "Although to our knowledge c-MET expressing lymphocytes have not be found in human NSCLC cancer there is evidence that subsets of lymphocytes may response to HGF in other types of human cancer." (PMID 32117721, 2020). "HGF/c-MET inhibition (Hi, Ci or Hi + Ci) did not alter cancer cell proliferation." (PMID 32203220, 2020). "Thus, the observed absence of metastasis in the triple therapy group may also reflect the important contribution of the HGF/c-MET inhibition component of the triple therapy, which significantly downregulates EMT of cancer cells." (PMID 32203220, 2020). "We found that while HGF or c-MET inhibition alone had variable effects on cancer migration, stemness and EMT, simultaneous inhibition of both the ligand and receptor (Hi + Ci) consistently reduced cancer cell migration/invasion into collagenous matrices, stem cell marker expression and EMT." (PMID 32203220, 2020). "In addition, CDDP practically induced cancer vaccination in the absence of MET (from 0 to 60% of the mice)." (PMID 32764535, 2020). "The potential for c-MET to influence both immunoregulatory molecules in MET dependent cancers and leukocytes in either MET dependent or MET independent cancer raises the possibility that treatments targeting the c-MET axis could impact on the outcomes of anti-cancer immunotherapies." (PMID 32117721, 2020). "However, more frequently, MET signalling is activated by the hepatocyte growth factor/scatter factor, HGF, produced by adjacent mesenchymal tissues, including stromal components of cancers." (PMID 31296956, 2019).
cancer (continued). "Thus, combined MET and CDK4/6 inhibition synergises broadly across cancer histio- and genotypes." (PMID 31296956, 2019). "In addition, we also tested the antitumour activity of three cancer cell lines without MET gene amplification/activation, including DLD1, MDA-MB-231 and A549." (PMID 31137515, 2019). "However, patients with c-MET-positive cancers had significantly shorter PFS (median in months: 11.5 vs. 17.6, P = 0.039) and OS (median in months: 17.0 vs. 24.3, P = 0.043) compared with those of patients with c-MET negative cancers." (PMID 31395059, 2019). "Interestingly, STAT3 activation seems to be a general mechanism of acquired resistance since it was also observed in cancer cells driven by diverse kinases, including EGFR, HER2, ALK, and MET, as well as mutant KRAS following treatment with specific inhibitors." (PMID 30622697, 2019). "Therefore, dual inhibition of MET and VEGF pathways may critically disrupt angiogenesis, tumorigenesis and progression of cancers." (PMID 29712569, 2018). "Moreover, mounting experimental and clinical evidence have also suggested a central role for the signaling networks operating to promote a metastatic and/or therapeutic resistance cascade in cancer development that involves interactions of AR, TMPRSS2, HGF and c-MET with critical components of TMEs." (PMID 29587825, 2018). "However, that there is a precedent for functional and therapeutically actionable EGFR, MET, and BRAF kinase domain duplications in other cancers is suggestive that a similar mechanism may be applicable to the observed RET kinase duplications in breast cancer." (PMID 30446652, 2018). "Indeed, MET interacts with several other receptor tyrosine kinases (RTKs) and MET heterodimers with EGFR, RON, HER2 and HER3 have been found abundant in MET-amplified cancer cells." (PMID 28968967, 2017). "The discrepancy between the results of these studies and our data suggests that in the presence of a continuous source of HGF secretion (i.e. PSCs) as in our study, c-MET inhibition alone may not be sufficient to significantly reduce cancer progression." (PMID 29100344, 2017). "MET, the receptor tyrosine kinase (RTK) for scatter factor/hepatocyte growth factor, is involved in acquisition and maintenance of critical oncogenic and invasive features in several types of human cancer and represents a promising molecular therapeutic target." (PMID 28532501, 2017). "In the past two decades, several monoclonal antibodies (mAbs) against the HGF/c-MET signaling pathway including rilotumumab, ficlatuzumab, DN30, and onartuzumab, among others, have been extensively studied in preclinical and clinical trials, with promising outcomes in cancer treatment." (PMID 28485003, 2017). "Interestingly, the targetable genes (by administering e.g. cobimetinib, trastuzumab, and ponatinib, respectively, against) MET, HER2, and FGFR2 also displayed the highest difference with a fold change of the mean expressions over 2 when comparing gastric normal and cancer samples." (PMID 27384994, 2016). "Finally, and in accordance with previous suggestions in different cancer types, we propose that the HGF/MET pathway might act as a primary resistance mechanism for EGFR inhibitors." (PMID 26319934, 2015). "It is expected that ddPCR may have good application prospects in molecular cancer diagnosis, for example in the study of phosphoinositide-3-kinase, catalytic subunit α (PIK3CA), MET proto-oncogene (MET; hepatocyte growth factor) and Kirsten rat sarcoma viral oncogene homolog (K-RAS)." (PMID 25780439, 2015). "In addition, we detected some other ‘cancer stemness’ markers (e.g. LGR4, SOX9, KLF5, MET) as well as pancreatic embryogenesis-related factors which may be re-initiated in CSC (e.g. HNF4A)." (PMID 24069258, 2013). "Accordingly c-MET could only be used as a prognostic marker in certain cancer types, but not in others." (PMID 23251249, 2013).
cancer (continued). "Amplification or over-expression of c-MET (the receptor for HGF) is a known genetic aberration and therapeutic target in squamous NSCLC and PAK1 may be a key effector for HGF/c-MET signaling in cancer." (PMID 21653999, 2011). "In contrast, the immune-activated subtype, which exhibits spatial co-option of PD-L1+ cancer cells and pro-inflammatory signatures, shows durable responses to immunotherapy and may benefit from the combination of immune checkpoint inhibitors (ICI) and MET-TKIs." (PMID 40703266, 2025). "Therefore, co-treatment with c-MET inhibitors could potentially improve responses to cancer immunotherapy by reducing neutrophil-mediated immunosuppression and enhancing T cell activity, even in tumors that are not inherently dependent on c-MET." (PMID 39664377, 2024). "Interestingly, the opposite pattern was observed for the MET/ESR2 coexpression in which high coexpression was associated with younger age at diagnosis, increased NPI, advanced stage and grade of carcinoma, hormone receptor-negative status, and non-luminal tumors." (PMID 39742369, 2024). "For tumors expressing wt MET (the vast majority of patients), a priori ineligible for MET-targeted therapies, it should be noted that hampering the MET signaling reduces migration and metastatic dissemination drastically without affecting the growth of cancer cells." (PMID 37760640, 2023). "Given the relatively novel discovery of MET exon 14-skipping mutations in LUAD, there is a lack of insight towards how the METΔex14 oncogene aberrantly engages its parallel downstream signaling pathways, especially compared to its role when amplified in other oncogene-driven cancers." (PMID 35326531, 2022). "Thus, to further clarify how MET is expressed in MM, we investigated the frequency of MET-GCNG/GA and expression by FISH and IHC in 155 consecutive MM cases, employing strictly defined criteria previously applied to a cancer type with significant heterogeneity of MET abnormalities, such as NSCLC." (PMID 34884673, 2021). "Moreover, we also found that osimertinib alone did not affect pERK activity and increased pAKT expression in EGFR/MET-driven tumors, which could provide pro-survival signals to the cancer cells even in the absence of pEGFR." (PMID 34298655, 2021). "However, cancers with no amplification can show MET overexpression and respond to MET inhibitors." (PMID 32549194, 2020). "Our data suggested that inhibition of MET and AXL phosphorylation activities through LY2801653 in turn led to marked suppression of downstream oncogenic signaling pathways, which might play important roles in proliferation and angiogenesis‐related behaviors of cancer." (PMID 34766112, 2020). "In addition, in line with the effects of etoposide treatment, TOP2B silencing induced MET and downregulated STT3 and PD-L1 in spheres (left), resulting in reduced PD-1 binding (upper right) and sensitization of sphere cells to PBMC-mediated cancer cell killing in vitro (bottom right)." (PMID 29765039, 2018). "Importantly, in view of therapy development, the MET and EGFR tyrosine kinases are actionable therapeutic targets due to their high expression in TNBC and several selective kinase inhibitors of which both are FDA approved for other cancers or in clinical trials." (PMID 30227653, 2018). "Interestingly, whereas these variations have been found in tumors and germlines of cancer patients and appear to increase MET signaling in vitro, they are not in the kinase domain itself, and there is considerable debate as to their transforming oncogenic capacity." (PMID 26934580, 2016). "Moreover, in this model, hepatocyte growth factor (HGF) was up-regulated and complementary activation of the HGF receptor MET was detected in tissues where TβRII had been ablated, which implicates this paracrine signaling network as a potential mechanism for regulation of carcinoma development." (PMID 22943793, 2012).